MMP13 (matrix metallopeptidase 13)
Diseases named in the same sentence as MMP13 in open-access papers (continued):
Sharing a sentence is not in itself a finding about the gene and the disease.
cancer (continued). "In addition, some MMPs including MMP-1, MMP-2 and MMP-13 are involved in Wnt-5a mediated invasion of cancer cells." (PMID 21998657, 2011). "Interestingly, a strong correlation between MMP-13, both in cancer cells (p = 0.015) and peritumoral fibroblasts (p < 0.001), was observed with Her-2/neu nuclear staining." (PMID 18373849, 2008). "Several MMPs within this amplicon have been previously implicated in cancer, however the only one of these genes implicated by our insertions is Mmp13, which to date has not been ascribed a role in cancer." (PMID 18485879, 2008). "High levels of MMP-13 in cancer cells correlated with the expression of the Her-2/neu protein." (PMID 18373849, 2008). "We identify several novel candidate cancer genes including Rreb1, Mmp13 and Arfrp2 (Arl15)." (PMID 18485879, 2008). "Moreover, MMP13 was correlated with many immune checkpoints in pan-cancer." (PMID 38066539, 2023). "It is possible that such an MMP-13/MMP-9 activation cascade may also exist in cancer." (PMID 35805035, 2022). "Thus, the value of abnormal MMP-13 expression in cancer tissues and its role as a prognostic marker or therapeutic target could further be evaluated." (PMID 34452576, 2021). "Since paclitaxel shows strong efficacy in the treatment of carcinomas, an epithelial-derived cancer cell type, this chemotherapeutic agent could similarly induce mitochondrial dysfunction in basal epidermal keratinocytes, leading to MMP-13 upregulation and axon degeneration." (PMID 32132628, 2020). "Moreover, MUC1 induces cancer cell metastasis by upregulating MMP13 in ESCC15." (PMID 27245877, 2016). "Therefore, the expressed MMP9 and MMP13 are able to regulate the metastasis of cancer cells." (PMID 25866480, 2015). "The catalytic activity of MMP13 may play a role in the high invasion capacity of cancer cells." (PMID 24658133, 2014). "Additionally, MMP-13 has been identified as a hypoxia-induced gene in carcinoma cells." (PMID 19426483, 2009). "On the other hand, the -77 A/G polymorphism in the promoter region of MMP13, which modifies a PEA3 binding site resulting in reduced transcriptional activity of this gene, might contribute to reduce the risk of developing cancer." (PMID 19094243, 2008). "On the other hand, the polymorphism -77 A/G in the promoter region of MMP13, which modifies a PEA3 binding site, results in a reduced transcriptional activity of this gene, which might contribute to reducing the risk of developing cancer." (PMID 19094243, 2008). "Research indicates that NFATC2 regulates the expression of matrix metalloproteinase 13 (MMP13) in BC cells through interactions with other proteins, thereby promoting the invasiveness of cancer cells, which provides a new therapeutic target for BC treatment." (PMID 40496857, 2025). "Key oncogenes, including SERPINE1, MMP13, INHBA, and SPARC, emerged as central to these effects, consistent with their reported contributions to cancer progression across various malignancies." (PMID 40361356, 2025). "Matrix metalloproteinases (MMPs), particularly MMP13, MMP1, and MMP7, are known to play a significant role in cancer progression." (PMID 38707175, 2024). "Eight hub genes (MMP1, MMP7, MMP13, LAMC2, LAMB3, PLAU, COL7A1, and SPP1) were upregulated in both HNSCC and LSCC, suggesting a significant role in cancer progression." (PMID 38707175, 2024). "Several studies have demonstrated that MMP1, MMP2, MMP9, MMP13 and MMP19 in some cancer tissues such as NSCLC or gastric cancer are all raised, and these MMP members can degrade basement membrane and open the channel for cancer’s invasion and metastasis." (PMID 38560562, 2024). "mRNA expression levels of MMP-12, MMP-13, MMP-14, and MMP-19 in the cervical tissue of patients with cancer were greater than that observed in the control (p = 0.045, p = 0.025, p = 0.003, and p = 0.025, respectively)." (PMID 39247608, 2024).
cancer (continued). "MMP13’s capability to degrade collagens and other ECM components enables cancer cells to navigate through the physical barriers and intravasate into the circulatory system, propelling metastatic spread." (PMID 38066539, 2023). "Many of the genes upregulated, i.e., MMP1, MMP13, S100A7, CEMIP, and CA9 are known to increase in various cancer cells." (PMID 36766731, 2023). "Using an in vitro cell-based system, it was demonstrated that RKIP inhibits the transcription of several MMP transcripts including MMP1-3, MMP10, and MMP13 in cancer cells." (PMID 36765912, 2023). "MMP13 expression was increased further in IDC cases, with MMP13 expression detected in both myofibroblasts and cancer cells." (PMID 36864079, 2023). "Meanwhile, we noted that Matrix Metalloproteases (MMPs), including MMP1, MMP3, MMP7, MMP10 and MMP13 genes were significantly upregulated in the BSE group, and they were almost universally upregulated in cancer." (PMID 37697300, 2023). "Cancer aggressiveness-related proteins, such as N-cadherin, Vimentin, Twist, MMP-2, MMP-9, and MMP-13, and the glycolytic enzymes PKM2 and GLUT1 were upregulated in ERL-R cells." (PMID 36611972, 2023). "MMP13 knockdown significantly reduced invasion enhanced by HBP1 siRNA, suggesting a role of MMP13 in cancer invasion and metastasis." (PMID 36677584, 2023). "MMP-14 has a central role among the MMPs and acts in cancer metastasis by degrading the ECM, increasing the secretion of pro-MMP2, pro-MMP9 and pro-MMP13, while cleaving membrane-anchored growth factors and cytokines." (PMID 36656313, 2023). "Most MMPs have consistently increased gene expression across cancers, and MMP1, MMP9, MMP10, MMP11, and MMP13 are almost universally upregulated across a wide variety types of cancers." (PMID 36903626, 2023). "Cytohubba analysis of these genes revealed 13 hub genes, of which MMP13, POSTN, SFRP4, ADAMTS16 and FNDC1 were significantly altered in their expression with CTHRC1 and seen to affect survival across cancers." (PMID 36190948, 2022). "This review summarizes our current understanding of the regulation of MMP-13 expression and secretion and discusses the actions of MMP-13 in cancer progression and metastasis." (PMID 35805035, 2022). "MMP13 plays a crucial role for epithelial-mesenchymal transition (EMT) and therefore for cancer progression." (PMID 35311102, 2022). "Considerable evidence has shown that MMP-13-mediated degradation and remodelling of ECM plays a very important role in cancer pathogenesis and metastasis." (PMID 35805035, 2022). "Sirtuin 1, known as NAD-dependent deacetylase sirtuin-1, promoted cancer cell proliferation and metastasis via STAT3/MMP-13 signaling, which is also found participated in the abnormal metabolism pathways in AML." (PMID 36727051, 2022). "It would hence be of interest to look at the protein expression data in cancers for CTHRC1 and the now identified genes of interest, POSTN, MMP13, SFRP4, ADAMTS16 and FNDC1." (PMID 36190948, 2022). "In the present study, we uncovered a new regulatory mechanism of cancer invasion by linking ABL to RUNX2 and MMP13." (PMID 34136397, 2021). "These cytokines have been identified to be directly or indirectly responsible for cancer progression through remodeling of ECM by upregulating the expression of molecules such as MMP2, MMP3, MMP9, MMP10, MMP13, PLAU, ICAM1 and VCAM1." (PMID 34946170, 2021). "In the PDX model, most downregulated genes affected by OC-X treatments included MMP9, CXCL12, MMP13, and POSTN within the selected cancer stages." (PMID 34069906, 2021). "It has been revealed that MMP-3 and MMP-13 mediate the remodeling of ECM and contribute to the metastasis of cancer cells." (PMID 32711573, 2020). "As COL1A1 and MMP13 have been reported to be correlated to the metastasis of several types of cancers, GEPIA database was used to confirm the high expression of MMP13 and COL1A1 in TC tissues, showing correlated with TNM stage." (PMID 33014334, 2020).
cancer (continued). "Seven MMPs (MMP7, MMP11, MMP12, MMP13, MMP24, MMP27, and MMP28) had an AUC of greater than 0.95 for at least one cancer type." (PMID 31200666, 2019). "Aside from KIRP and PRAD for MMP13, and KICH and UCEC for MMP11, the upregulation was consistent across all cancer types." (PMID 31200666, 2019). "This grouping in cluster 2 features high expression of gene cluster B genes (MMP3, MMP10, MMP13, MMP1, and MMP12) in a pattern that is relatively unique among cancer types." (PMID 31200666, 2019). "We also detected upregulation of genes involved in cancer metastasis and cancer stemness (FOXC2, SNAI2, CXCRs, and IGF1), cell stemness (NANOG, POU5F1, and KLF4), metalloproteinases (MMP7, MMP10, and MMP13), and angiogenic factors (IL-8 and S1PR1)." (PMID 28423353, 2017). "From various cancer formation and metastasis signals, it can be seen that a set of matrix metalloproteases (MMPs) (MMP27, MMP23B, THBS2, MMP13, MMP11) as well as the MMPs receptor ITGB3 were inhibited in GX0101-infected CEFs." (PMID 27200301, 2016). "While restoration of RKIP in low-RKIP-expressing invasive cancer cells suppressed MMP13 expression and inhibited invasion, silencing of RKIP in high-RKIP- expressing non-invasive cells increased MMP13 expression." (PMID 26308852, 2015). "In human cancer cells, MMP-1, MMP-2, MMP-3, MMP-9, and MMP-13 have been found to be correlated with malignant grade and metastasis." (PMID 24047437, 2013). "Previous studies have demonstrated that treatment of TLR9-expressing cancer cells with synthetic TLR9 ligands, which mimic the structure of bacterial DNA, stimulates their invasion in vitro through matrix metalloproteinase-13 (MMP-13) activation." (PMID 23761830, 2013). "Subsequently, the cancer invasion factors uPA, MMP-1 and MMP-13, and cell invasiveness, were decreased." (PMID 23401122, 2013). "It is therefore conceivable, that the results presented in this study also provide mechanistic insight into the role of MMP-13 and MMP-1 in the progression of these malignant tumors." (PMID 22880047, 2012). "Additionally, MMP13 was strongly upregulated, reinforcing its function in ECM turnover and cancer invasiveness." (PMID 40604111, 2025). "Compared with other cancers, EFNA1 and MMP13 were highly or moderately expressed in GC." (PMID 38987376, 2024). "The differences in the proteolytic cascade and preferred substrates may explain the distinct roles of MMP3 and MMP13 in the TME: MMP13 may be more specialized for the regulation of ECM integrity, while MMP3 may have broader roles in cancer progression." (PMID 38774209, 2024). "Furthermore, western blotting (WB) was used to verify the expression of MMP13 and epithelial-mesenchymal transition (EMT) factors in cancer tissues." (PMID 37000142, 2023). "Osteocytes also express different matrix metalloproteinases (i.e., MMP2, MMP13, and MMP14), which could assist metastatic cancer cells in migrating through the extracellular matrix and invading the bone." (PMID 37174109, 2023). "Interestingly, stromal Mmp13 expression was localised to the periphery of collectively invading cancer cells, compared to non-invasive areas of DCIS where Mmp13 expression was significantly reduced." (PMID 36864079, 2023). "Likewise, the TLR9 agonist unmethylated oligonucleotide CpG, which is recognized as a bacterial DNA by TLR9, increases MMP-13 expression and activity, reduces TIMP-3 synthesis and the invasion capacity of breast MDA-MB-231 cancer cells." (PMID 38069210, 2023). "Furthermore, miR-150 regulates cancer cell migration by affecting multiple effectors including matrix metalloproteinases (MMP14 and MMP13), cell adhesion molecules (ITGA3, ITGA6), transcription factors (MYB), and epigenetics factors (HMGA2 and EZH2)." (PMID 37924077, 2023). "We also discovered that epiberberine inhibited HNSCC metastasis through the inhibition of MMP‐13, suggesting that MMP‐13 may be a potential target to against cancer metastasis." (PMID 37710409, 2023).
cancer (continued). "The upregulation of MMPs (MMP2, MMP9, and MMP13) was also reported in cancers overexpressing IL-32 along with other EMT markers including vimentin, Slug, Snail, and ZEB1, as well as they are well known for their contribution to cancer metastatic." (PMID 35281008, 2022). "Given its powerful and destructive action toward ECM, it is not surprising that higher MMP-13 expression frequently occurs in cancer." (PMID 35805035, 2022). "Our study in evaluating 1027 matrisome genes across cancers, has identified a novel set of genes (MMP13, FNDC1, SFRP4 and ADAMTS16) that could work with CTHRC1 to regulate cancer progression." (PMID 36190948, 2022). "Therefore, these compounds are predicted to inhibit growth and induce apoptosis of cancer cells through their interactions with MMP12, MMP13, CDK4, JAK3, VEGFR1, VEGFR2, and KCNA3." (PMID 36106139, 2022). "Osteomimetic features adopted by cancer cells involve the expression of bone-related molecules such as osterix, osteoprotegerin (OPG), runt-related transcription factor (RUNX2), metalloprotease (MMP) 9, MMP-13, and cathepsin K44,45." (PMID 34018387, 2021). "Various in vitro and in vivo assays highlight that ginsenosides including compound K (CK), Rg1, Rg3, Rh1, Rh2 and Rd reduced metastatic abilities of various tissue-specific cancer cells by down-regulating the transcriptional expressions of several MMPs (MMP-1, MMP-2, MMP-3, MMP-7, MMP-9 and MMP-13)." (PMID 33671187, 2021). "Previous studies indicated that circRNA_100876 was involved in the regulation of matrix metallopeptidase 13 (MMP13) expression, and MMP13 had been identified as a significant regulators of cancer cell migration and invasion abilities via degrading extracellular matrix." (PMID 33262782, 2020). "MMP13 and MMP12 are involved in carcinomas and inflammatory conditions." (PMID 30765775, 2019). "The role of MMP-13 in PAR1-mediated activation in cancer has not been well studied except in context of tumor cell expression." (PMID 30065181, 2018). "However, it appears that MMPs are important enzymes involved in local attack and metastatic PTC cancer, being reported in several studies related to different members of the MMP family, including MMP-1, MMP-2, MMP-7, MMP-9, MMP-10, MMP-13, MMP-14 and MMP-15." (PMID 30509240, 2018). "Direct pharmacologic comparative studies in relevant cancer cell lines between vorapaxar, atopaxar, PZ-128 and other PAR1-derived pepducins using a set of proteases agonists such as thrombin, MMP-1, MMP-13 and elastase could address this question." (PMID 30065181, 2018). "Moreover, transcripts of MMP13, which belongs to a matrix metalloproteinase family that contributes to extracellular matrix (ECM) breakdown and cancer cell migration, exhibited greater levels (2.0 fold) in the 4-NQO(E) group than the UNT(E) group." (PMID 26110572, 2015). "MMP-13, a crucial enzyme, degrades collagen types I, II, and III, leading to cartilage breakdown, and exhibits high expression levels in patients with several pathological diseases, such as OA, RA, and cancer." (PMID 25147440, 2014). "This regulation is in line with pro-metastatic ability of mp53 (gain-of-function feature), however our data do not suggest a direct involvement of p63/MMP13 axis in cancer progression." (PMID 24658133, 2014). "In addition to MMP12 (present study), MMP1, MMP13 and MMP28 have also been shown to promote invasion and metastasis in various cancers." (PMID 24885469, 2014). "Our clinical analyses suggest that p63-dependent regulation of MMP13 has not direct impact on survival outcome of cancer patient." (PMID 24658133, 2014). "It has been reported that MMP-13 and FAK expression is involved in cancer cell migration." (PMID 24599080, 2014). "Otherwise, as recently reported in human cancers, Wnt5a/Ror2 signaling may up-regulate the expression of matrix metalloproteinases (MMPs) such as MMP1, MMP2, and MMP13 to increase cell invasiveness." (PMID 25211363, 2014).
cancer (continued). "MMP-13 detected either in cancer cells or in adjacent fibroblasts, was not correlated with MMP-2 or MMP-9." (PMID 18373849, 2008). "Additionally, MMP-13 may activate pro-MMP-9, thus facilitating vascular intravasation and extravasation by cancer cells." (PMID 41471689, 2025). "MMP13 and its activator MMP3 may be used as biomarkers for cancer progression." (PMID 38774209, 2024). "In our study we could not find any significant correlation between MMP-13 expression in cancer cells and peritumoral fibroblasts and expression of the Her-2/neu protein and ER." (PMID 34452576, 2021). "If serum detection is achievable, ubiquitously upregulated MMPs such as MMP11 or MMP13 could serve as a pan-cancer marker, capable of identifying the presence of cancer but not the specific location of the cancer." (PMID 31200666, 2019). "In addition, YB-1 was shown to affect the expression of MMP13 in A375 cancer cell line without binding to the AP-1 binding site of MMP13 gene promoter." (PMID 29320405, 2018). "In addition, the cancer cell-derived osteoclast-activating factors MCSF, IL-6, IL-8, RANKL, MMP2, MMP13, RUNX2 and PTHrP are significantly down-regulated in MDA-MB-231 cells transfected with miR-124 mimic and up-regulated in MCF7 cells transfected with miR-124 inhibitor." (PMID 29343249, 2018). "Moreover, the chemokine receptor CCR4 might be involved in TNF-α-induced expression of MMP13 in CRC cells, suggesting the drugs targeting CCR4 may provide a clue for antagonizing TNF-α-regulated cancer cells metastasis." (PMID 27356745, 2016). "Such factors, which include the collagenases MMP-1 and MMP-13 and the stromelysin MMP-3, have well documented roles in disease progression and can in particular aid cell penetration through extracellular matrices, supporting invasion and metastasis in several cancer types." (PMID 25596732, 2015). "The catalytic activity of MMP13 is required in high invasion capacity of metastatic cancer cells, however, although p63 and MMP13 expression correlates in cancer patients, their co-expression does not predict cancer patient survival." (PMID 24658133, 2014). "However, in vivo studies in mouse cancer models suggest that TSPAN8 enhances cancer cell motility and migration mainly by recruiting integrins, whereas CD151 efficiently recruits and activates MMP9 and MMP13 to facilitate the degradation of the ECM and the invasion of tumor cells." (PMID 38275818, 2024). "Therefore, RKIP may inhibit cancer cell invasion by down-regulating MMP13 expression through negative effects mainly on Erk pathway." (PMID 26308852, 2015). "Thus, MMP13 represents a negative prognostic factor for different cancers." (PMID 24658133, 2014). "MT1-MMP stimulates epithelial cell, fibroblast, and cancer cell invasion into collagen, while the other collagenases (MMP-1, MMP-2, MMP-8, and MMP-13) do not." (PMID 24549119, 2014). "As in human tumors, Mmp13 mRNA was found in myofibroblasts of invasive grade II and III carcinomas, but not in benign grade I and II mammary intraepithelial neoplasias." (PMID 18698413, 2008). "High levels of MMP13 and its activator MMP3 promote cancer progression rather than T cell response." (PMID 38774209, 2024). "Although Raf/MEK/ERK-mediated regulation of transcription factors is involved in the regulation of MMP13 by RKIP, it has been determined that this pathway is not required for the observed invasive nature of cancer cells with regards to RKIP and MMP1 and MMP2 in vitro." (PMID 36765912, 2023). "There are now some selective MMP inhibitors developed for the treatment of the non-neoplastic disorders and cancer, such as MMP-13 inhibitors in OA, MMP-14 inhibitors in RA and cancer and MMP-12 inhibitors in COPD, all of which have been proven to be effective in animal models." (PMID 27455234, 2016).